SOCS7 (suppressor of cytokine signaling 7)
Diseases named in the same sentence as SOCS7 in open-access papers (continued):
Sharing a sentence is not in itself a finding about the gene and the disease.
tumor (11 papers, 2010 to 2026). "We further investigated the underlying mechanism of SOCS7’s anti-tumor effect; we performed a proteomics analysis to identify candidate proteins associated with SOCS7 and found that HuR was one of the top-ranked proteins." (PMID 35624501, 2022). "To summarize, SOCS7 is downregulated in HGSOC tumor, and its expression is associated with the clinicopathologic features and survival probability of HGSOC patients, demonstrating its correlation with HGSOC prognosis." (PMID 35624501, 2022). "We further examined the function of HuR in HGSOC to investigate the mechanism underlying the tumor-inhibitory effect of SOCS7." (PMID 35624501, 2022). "There was a trend for tumours with lower SOCS7 expression levels to be associated with shorter DFS and OS times." (PMID 20433750, 2010). "Mechanistically, tumor-derived SERPINE1 drives TAM M2 polarization through the let-7g-5p/SOCS7/STAT3 axis, promoting GC progression and therapeutic resistance." (PMID 41601623, 2026). "Gain/Loss-of-function examinations were carried out to assess the effectiveness of SOCS7 in cell viability, cell cycle, and tumor growth of HGSOC." (PMID 35624501, 2022). "Meanwhile, based on the analysis of tissues collected from patient cohort 1, we observed that the transcript level of SOCS7 in the tumor tissues from the HGSOC patients was significantly (P < 0.001) lower than that in the paired normal tissues." (PMID 35624501, 2022). "The expression levels of FOXM1 and HuR in tumor xenografts were also decreased after SOCS7 overexpression." (PMID 35624501, 2022). "In the current study, we observed that one of the SOCS family members, SOCS7, was downregulated in the tumor tissues in HGSOC patients." (PMID 35624501, 2022). "Meanwhile, HuR overexpression counteracted the tumor-suppressive effect of SOCS7, demonstrating the interplay between these two proteins in HGSOC pathogenesis." (PMID 35624501, 2022). "The DFS and OS curves for women with tumours which were classified as having 'high levels' of SOCS7 transcript were found to differ significantly from those of their 'low level' counterparts." (PMID 20433750, 2010). "Our results show decreased SOCS 1,4,5,6 and 7 expression with increased TNM stage and decreased SOCS7 expression with higher tumour grade." (PMID 20433750, 2010). "Furthermore, immunohistochemical examination of SOCS7 and pSTAT3 on consecutive sections of miR‐199‐positive PDAC tissue showed weak SOCS7 expression and relatively strong nuclear pSTAT3 expression in tumor cells." (PMID 39431622, 2024). "We next evaluated the effect of SOCS7 overexpression on HGSOC tumor growth in vivo." (PMID 35624501, 2022). "SOCS7 has been identified as having a potential tumor suppressor role." (PMID 36169255, 2022). "Meanwhile, SOCS7 may also possess an intriguing role in regulating cell cycle and tumor suppression." (PMID 35624501, 2022). "Furthermore, for SOCS7, four studies reporting increased expression and two reporting decreased expression in tumor tissues were identified." (PMID 34120621, 2021). "Considering that SOCS family proteins function as a terminator of LR, the suppression of SOCS1, SOCS3, and SOCS7 expression in remnant livers may be involved in the accelerated tumor development in HBx transgenic mice after PH." (PMID 29729074, 2018). "Less data is available on the tumour suppressor activity of SOCS7 and CIS." (PMID 24757565, 2014). "SOCS7 expression decreased with higher tumour grade (Grade 3 vs. Grade 2 p = 0.037)." (PMID 20433750, 2010). "Based on the dataset from TCGA, we found that the transcript levels of SOCS7 in HGSOC patients with tumor stages 3 (P < 0.01) and 4 (P < 0.05) were significantly lower than that in the patients with tumor stage 2." (PMID 35624501, 2022). "SOCS7 acted as a HGSOC suppressor by inhibiting cancer cell viability and tumor growth in vivo." (PMID 35624501, 2022).
tumor (continued). "SOCS7 knockdown can result in increased MCF7 and MDA-MB-231 basal cellular growth and migration in vitro and can positively influence the growth of MCF7 in vivo tumour xenografts in nude athymic mice." (PMID 25162020, 2014). "SOCS7 transcript levels did not significantly differ with different tumour grades or with ER status." (PMID 20433750, 2010).
cancer (8 papers, 2014 to 2025). A tumor composed of atypical neoplastic, often pleomorphic cells that invade other tissues. "The results suggest that SERPINE1-mediated cancer-derived exosomal let-7 g-5p downregulates SOCS7 protein levels, reducing its interaction with STAT3, which leads to STAT3 hyperphosphorylation and promotes M2 polarization." (PMID 39748408, 2025). "We did not identify significant differences in the expression of SOCS1 or SOCS7 between cancer and normal samples." (PMID 34120621, 2021). "CCND1 (FC 2.59), BCL2L1 (FC 2.25), MYC (FC 3.70), along with CCND2 (FC 1.60) and SOCS7 (FC 1.51), are all located downstream of STAT activation and were upregulated in carcinoma tissue." (PMID 30603058, 2018).
infection (2 papers, 2021 to 2022). The state of being infected such as from the introduction of a foreign agent such as serum, vaccine, antigenic substance or organism. "Notably, putative tuberin (Gene.10133::comp2839) was detected at all four post-infection timepoints, whereas tubulin tyrosine ligase-related protein (Gene.29353::comp15247) and suppressor of cytokine signaling 7 (Gene.22611::comp7045) were identified in the early stages of infection (14 days)." (PMID 36227939, 2022).
SOCS7 also shares sentences with these, for which no sentence is quoted: Autoimmunity (1 paper); gouty arthritis (1); immune diseases (1); multiple sclerosis (1); Sepsis (1); serous ovarian carcinoma (1).